ATXN3 (ataxin 3)
Description:
Deubiquitinating enzyme involved in protein homeostasis maintenance, transcription, cytoskeleton regulation, myogenesis and degradation of misfolded chaperone substrates. Binds long polyubiquitin chains and trims them, while it has weak or no activity against chains of 4 or less ubiquitins. Involved in degradation of misfolded chaperone substrates via its interaction with STUB1/CHIP: recruited to monoubiquitinated STUB1/CHIP, and restricts the length of ubiquitin chain attached to STUB1/CHIP substrates and preventing further chain extension (By similarity). Interacts with key regulators of transcription and represses transcription: acts as a histone-binding protein that regulates transcription. Acts as a negative regulator of mTORC1 signaling in response to amino acid deprivation by mediating deubiquitination of RHEB, thereby promoting RHEB inactivation by the TSC-TBC complex. Regulates autophagy via the deubiquitination of 'Lys-402' of BECN1 leading to the stabilization of BECN1.
Synonyms: ATX3; MJD; MJD1; SCA3; JOS; AT3
Tractability: Small molecule: it has a high-quality binding pocket. Antibody: UniProt places it where antibodies can reach, with high confidence; its Gene Ontology location is reachable by antibodies, with high confidence; the Human Protein Atlas places it where antibodies can reach. PROTAC: UniProt records ubiquitination sites on it; ubiquitination databases record sites on it; its protein half-life has been measured.
Target class: Enzyme; Hydrolase
Gene: Protein-coding gene on chromosome 14 (92,044,496 to 92,106,622, reverse strand). Ensembl gene ENSG00000066427.
Subcellular location: Nucleus matrix; Nucleus; Lysosome membrane
Subcellular location (Human Protein Atlas): Nucleoli; Nucleoplasm; Plasma membrane
Pathways (Reactome):
Gene expression (Transcription): FOXO-mediated transcription of oxidative stress, metabolic and neuronal genes
Metabolism of proteins: Josephin domain DUBs
Gene Ontology:
Molecular function: ATPase binding; cysteine-type deubiquitinase activity; K48-linked deubiquitinase activity; K63-linked deubiquitinase activity; protein binding; ubiquitin protein ligase binding
Biological process: actin cytoskeleton organization; cellular response to amino acid starvation; intermediate filament cytoskeleton organization; microtubule cytoskeleton organization; negative regulation of TORC1 signaling; positive regulation of ERAD pathway; positive regulation of ubiquitin-dependent protein catabolic process; protein K48-linked deubiquitination; protein K63-linked deubiquitination; protein localization to cytosolic proteasome complex; regulation of cell-substrate adhesion; cellular response to heat; cellular response to misfolded protein; chemical synaptic transmission; monoubiquitinated protein deubiquitination; nervous system development; nucleotide-excision repair; proteasome-mediated ubiquitin-dependent protein catabolic process; protein deubiquitination; protein quality control for misfolded or incompletely synthesized proteins; ubiquitin-dependent protein catabolic process
Cellular component: cytosol; endoplasmic reticulum membrane; lysosomal membrane; nuclear matrix; nucleus; cytoplasm; mitochondrial matrix; mitochondrial membrane; nuclear inclusion body; nucleoplasm; synapse
Genetic constraint (gnomAD): Loss-of-function variants: 16 observed, 41.81 expected, observed/expected ratio (o/e) 0.38, 90% interval 0.26 to 0.58. The upper end of that interval is the gene's LOEUF score, 0.58, which puts it in group 2 of 6, group 1 being the genes least tolerant of losing a copy. Missense variants: 234 observed, 313.86 expected, observed/expected ratio (o/e) 0.75, 90% interval 0.67 to 0.83. Synonymous variants: 88 observed, 102.33 expected, observed/expected ratio (o/e) 0.86, 90% interval 0.72 to 1.03.
Homologues: Orthologues: chimpanzee ATXN3 (99% identical), macaque ATXN3 (98% identical), mouse Atxn3 (86% identical), rat Atxn3 (85% identical), tropical clawed frog atxn3 (70% identical), zebrafish atxn3 (61% identical), Caenorhabditis elegans atx-3 (31% identical). Paralogues in human: ATXN3L (69% identical).
Diseases named in the same sentence as ATXN3 in open-access papers:
ATXN3 is named in the same sentence as 170 diseases in open-access papers, as found by Europe PMC text mining. Sharing a sentence is not in itself a finding about the gene and the disease. The quoted sentences say what the papers report.
Spinocerebellar ataxia type 3 (198 papers, 2008 to 2026). "Spinocerebellar Ataxia Type 3 (SCA3) is a neurodegenerative dominantly-inherited disorder caused by an overexpansion of a CAG tract within the ATXN3 gene, conferring toxic properties to the ataxin-3 protein." (PMID 41830765, 2026). "Spinocerebellar ataxia type 3 (SCA3) is an autosomal dominant neurodegenerative disorder caused by CAG repeat expansion in the ATXN3 gene, typically onsetting in adults aged 30-40 years." (PMID 41736717, 2026). "Spinocerebellar ataxia type 3 (SCA3) is a dominantly inherited neurodegenerative disorder caused by a CAG trinucleotide repeat expansion in the ATXN3 gene." (PMID 41501569, 2026). "Spinocerebellar ataxia type 3 (SCA3) is a hereditary disease caused by abnormally expanded CAG repeats in the ATXN3 gene." (PMID 39849568, 2025). "Spinocerebellar ataxia type 3 (SCA3) is an uncommon inherited (autosomal dominant) neurodegenerative disorder caused by abnormal accumulation of ataxin-3 protein." (PMID 40190350, 2025). "Spinocerebellar ataxia type 3 (SCA3) is an adult-onset neurodegenerative disease caused by a polyglutamine expansion in the ataxin-3 (ATXN3) gene." (PMID 38227368, 2024). "Spinocerebellar ataxia type 3/Machado–Joseph disease (SCA3/MJD) is a neurodegenerative disorder caused by the ATXN3 CAG repeat expansion." (PMID 39125643, 2024). "Spinocerebellar ataxia type 3 (SCA3) is a rare neurodegenerative disease caused by an abnormal polyglutamine expansion within the ataxin-3 protein (ATXN3)." (PMID 37445783, 2023). "For example, VCP modulates the pathological phenotypes associated with ATXN3 mutations, which can cause spinocerebellar ataxia type 3 (Machado-Joseph Disease)." (PMID 37545006, 2023). "According to most literature reports, the abnormal expression of the ataxin-3 gene is mostly caused by spinocerebellar ataxia type 3 (SCA3)." (PMID 37269429, 2023). "CAG-polyglutamine (polyQ) repeat expansions in ATXN3 cause the neurodegenerative disorder spinocerebellar ataxia type 3 (SCA3)." (PMID 36737438, 2023). "Spinocerebellar ataxia type 3 (SCA3/MJD) is a neurodegenerative disease caused by CAG expansion in mutant ATXN3 gene." (PMID 37033372, 2023). "An expanded polyQ mutation in the DUB ataxin-3 causes spinocerebellar ataxia type 3 (SCA3), providing a direct link between DUBs and neurodegeneration." (PMID 34689261, 2022). "Defects in ataxin-3 proteins and CAG repeat expansions in its coding gene ATXN3 cause Spinocerebellar Ataxia Type 3 (SCA3) or Machado-Joseph disease (MJD) polyglutamine neurodegenerative disease." (PMID 35851059, 2022). "Spinocerebellar ataxia type 3 (SCA3) is a dominantly inherited cerebellar ataxia caused by the expansion of a polyglutamine (polyQ) repeat in the gene encoding ATXN3." (PMID 35386195, 2022). "Spinocerebellar ataxia type 3 (SCA3/MJD) is caused by CAG expansion mutation resulting in a long polyQ domain in mutant ataxin-3." (PMID 34220448, 2021). "Spinocerebellar ataxia type 3 (SCA3) is an autosomal dominant neurodegenerative disease caused by expansion of a glutamine-encoding CAG repeat in the ATXN3 gene." (PMID 33994545, 2021). "Alterations in PNKP expression levels in humans have also been linked to the pathogenesis of spinocerebellar ataxia type 3 (SCA3) in combination with mutant Ataxin-3 (ATXN3)." (PMID 34226276, 2021). "Spinocerebellar ataxia type 3 is a condition characterized by progressive problems with movement due to mutations in the ataxin 3 gene." (PMID 34646114, 2021). "The pathology of spinocerebellar ataxia type 3, also known as Machado‐Joseph disease, is triggered by aggregation of toxic ataxin‐3 (ATXN3) variants containing expanded polyglutamine repeats." (PMID 31625269, 2020). "Ataxin-3 has been linked to neurodegenerative disease after unstable CAG repeat expansions in the ATXN3 gene were identified as the cause of spinocerebellar ataxia Type 3 (SCA3), also known as Machado-Joseph Disease, the most common autosomal dominant ataxia." (PMID 31379806, 2019).
Spinocerebellar ataxia type 3 (continued). "Spinocerebellar ataxia type 3 (SCA3) is caused by a CAG expansion in the ATXN3 gene, which leads to a polyQ expansion in the ataxin-3 protein." (PMID 30486313, 2018). "Spinocerebellar ataxia type 3 (SCA3) is one of nine polyglutamine (polyQ) neurodegenerative diseases caused by an abnormally long polyQ tract in the disease protein, which in SCA3 is ATXN3." (PMID 30231063, 2018). "Spinocerebellar ataxia type 3 (SCA3) is a dominantly inherited neurodegenerative disorder caused by a polyglutamine-encoding CAG repeat expansion in the ATXN3 gene which encodes the deubiquitinating enzyme, ATXN3." (PMID 30231063, 2018). "Ataxin-3, whose mutated form causes spinocerebellar ataxia type 3 (SCA3; also known as Machado–Joseph disease), is a polyQ protein with deubiquitinating function." (PMID 30460066, 2017). "Among these, polyglutamine (polyQ)-expanded ataxin-3 (Atx3) and huntingtin (Htt) are the main causative proteins of spinocerebellar ataxia type-3 (SCA3) and Huntington’s disease, respectively." (PMID 26808260, 2016). "Spinocerebellar ataxia type-3 (SCA3) is a neurodegenerative disorder caused by a polyglutamine repeat expansion in the ataxin-3 protein." (PMID 27731380, 2016). "Machado-Joseph disease or Spinocerebellar ataxia type 3 is a progressive fatal neurodegenerative disorder caused by the polyglutamine-expanded protein ataxin-3." (PMID 25144231, 2014). "Spinocerebellar ataxia type 3/Machado-Joseph disease (SCA3/MJD) is an autosomal dominant neurodegenerative disease caused by polyQ-expanded ataxin-3." (PMID 23382880, 2013). "Ataxin-3 misfolding and its subsequent aggregation underlies the autosomal dominant neurodegenerative disease Spinocerebellar ataxia type 3 (SCA3)." (PMID 23894474, 2013). "Note that mutant polyQ-expanded ataxin-3 is an aggregate-prone protein that causes spinocerebellar ataxia type 3 that is degraded by autophagy in a mouse model of this disease." (PMID 22518139, 2012). "Recent studies have revealed that bantam overexpression mitigates neurodegeneration induced by the pathogenic polyglutamine protein Ataxin-3, which is involved in the human disease spinocerebellar ataxia type 3 (SCA3)." (PMID 19107204, 2008). "Machado-Joseph Disease (MJD) or spinocerebellar ataxia type 3 (SCA3) is a neurodegenerative disease caused by Cytosine-Adenine-Guanine (CAG) triplet repeat expansions which result in an expanded polyglutamine tract in the ataxin-3 (ATX3) protein." (PMID 34064983, 2021). "A trinucleotide repeat expansion in ATXN3 could cause spinocerebellar ataxia type 3, a neurologic disorder that is characterized by progressive ataxia." (PMID 33541344, 2021). "Among these, ataxin-3 (AT3) is the causative agent of spinocerebellar ataxia type-3." (PMID 23251648, 2012). "Interestingly, mutant ataxin-3, which is the protein product of the gene mutated in spinocerebellar ataxia type 3 (SCA3), was shown to bind to ITPR1 and thereby cause a destabilization of neuronal calcium signaling." (PMID 19461874, 2009). "BACKGROUND: Spinocerebellar ataxia type 3 (SCA3/Machado-Joseph disease), an incurable autosomal dominant neurodegenerative disorder, is caused by cytotoxic aggregation of polyglutamine-expanded ataxin-3 protein." (PMID 41715186, 2026). "Spinocerebellar ataxia type 3 (SCA3) is a neurodegenerative disease caused by polyglutamine repeat expansion in the ATXN3 gene." (PMID 41613623, 2026). "The deubiquitinase Ataxin-3 causes spinocerebellar ataxia type 3 (SCA3) upon polyglutamine (polyQ) expansion." (PMID 42189036, 2026). "ATXN3 encodes the ataxin-3 protein, which contains a polyglutamine domain that is expanded in spinocerebellar ataxia type 3 (SCA3)." (PMID 41066632, 2025). "Spinocerebellar ataxia type 3 (SCA3) is a progressive neurodegenerative disease caused by an abnormal CAG repeat expansion within the ATXN3 gene, which encodes the ataxin-3 protein." (PMID 40468428, 2025).
Spinocerebellar ataxia type 3 (continued). "Spinocerebellar ataxia type 3 (SCA3) is a rare neurodegenerative disease caused by a CAG expansion of the ataxin-3 gene (ATXN3)." (PMID 40721863, 2025). "Spinocerebellar ataxia type 3 (SCA3), also known as Machado–Joseph disease, a rare autosomal dominant neurodegenerative disorder caused by cytosine–adenine–guanine repeat expansions in ATXN3, lacks effective therapies." (PMID 40797466, 2025). "Spinocerebellar ataxia type 3 (SCA3), caused by the abnormal expansion of polyglutamine (polyQ) in the ataxin-3 protein, is one of the inherited polyQ neurodegenerative diseases that share similar genetic and molecular features." (PMID 39765823, 2024). "ATXN3 polyQ is the pathogenic protein associated with spinocerebellar ataxia type 3 (SCA3), a dominantly inherited neurodegenerative disorder also called Machado-Joseph disease." (PMID 39715253, 2024). "Spinocerebellar ataxia type 3 (SCA3) is a neurodegenerative disease caused by a CAG repeat expansion in the ATXN3 gene." (PMID 36875652, 2023). "PolyQ tracts in ataxin 3, a deubiquitinase associated with spinocerebellar ataxia type 3 (SCA3), interact with beclin 1, a key initiator of autophagy." (PMID 36940239, 2023). "Spinocerebellar ataxia type 3 (SCA3) is a rare neurodegenerative disease caused by a trinucleotide (CAG) repeat expansion in exon 10 of the ATXN3 gene on chromosome 14 (p32)." (PMID 35489193, 2022). "Spinocerebellar ataxia type 3 (SCA3) is caused by the expansion of a glutamine repeat in the protein ataxin-3, which is deposited as intracellular aggregates in affected brain regions." (PMID 35741099, 2022). "CAG repeat expansion in exon 10 of the ATXN3 gene is known to cause spinocerebellar ataxia type 3 (SCA3) by resulting in an abnormally long polyQ tract in the encoded protein." (PMID 36127505, 2022). "Spinocerebellar ataxia type 3 (SCA3) is a neurodegenerative disorder caused by the expansion of a CAG repeat in the ATXN3 gene." (PMID 34878314, 2022). "In 304Q knock-in spinocerebellar ataxia type 3 (SCA3) mouse model, serum NfL and pNfH are elevated at the pre-symptomatic stage of 6 months of age and correlate with ataxin 3 aggregation and Purkinje cell loss in the brain." (PMID 34646114, 2021). "A polyglutamine expansion mutation in ataxin-3 causes spinocerebellar ataxia type 3 (SCA3), thereby providing a further link between ubiquitin-dependent protein quality control mechanisms and neurodegeneration 72,74." (PMID 33483467, 2021). "Abnormal expansion of a stretch of glutamine residues in the C‐terminus of ATXN3 is causative for spinocerebellar ataxia type 3 (SCA3), also known as Machado–Joseph disease, the most common hereditary type of ataxia." (PMID 31625269, 2020). "Spinocerebellar ataxia type 3 (SCA3) is an autosomal dominant neurodegenerative disorder caused by a CAG repeat expansion within the ATXN3/MJD1 gene." (PMID 31687087, 2019). "Spinocerebellar ataxia type 3 (SCA3) is a progressive neurodegenerative disorder caused by expansion of the polyglutamine repeat in the ataxin-3 protein." (PMID 29929540, 2018). "Spinocerebellar ataxia type 3 (SCA3) is caused by the expansion of a polyglutamine (polyQ) repeat in the protein ataxin-3 which is involved in susceptibility to mild oxidative stress induced neuronal death." (PMID 28912527, 2017). "Spinocerebellar ataxia type 3 (SCA3) is a currently incurable neurodegenerative disorder caused by a CAG triplet expansion in exon 10 of the ATXN3 gene." (PMID 28918024, 2017). "Machado-Joseph disease (MJD) or spinocerebellar ataxia type 3 (SCA3) is an autosomal dominant neurodegenerative disorder caused by expansion of the polyglutamine domain of the ataxin-3 (ATX3) protein." (PMID 27878228, 2016). "Ataxin-3 (ATX-3) is a ubiquitously expressed protein that mutated in a neurodegenerative disease called spinocerebellar ataxia type 3 (SCA3)." (PMID 27851749, 2016).